NANOG (Nanog homeobox)
Diseases named in the same sentence as NANOG in open-access papers (continued):
Sharing a sentence is not in itself a finding about the gene and the disease.
seminoma (35 papers, 2011 to 2026). A radiosensitive malignant germ cell tumor found in the testis (especially undescended), and extragonadal sites (anterior mediastinum and pineal gland). "Key transcription factors (TFs) such as TFAP2C, SOX17, OCT4/POU5F1 and NANOG are highly expressed in PGCs, and consequently are excellent diagnostic markers for seminoma and GCNIS14,18,19." (PMID 38123589, 2023). "Utilizing the SCENIC analysis on the non-seminoma tumor cells, we observed heightened activity of transcription factors quintessential for pluripotency maintenance, notably NANOG, POU5F1, and HDAC2, within the EC subset." (PMID 39528470, 2024). "In filamin A-deficient TCam-2 seminoma cells, enhanced transcript levels of the pluripotency factors OCT3/4, NANOG and FGFR3 compared to filamin A-proficient cells have been found, indicating that filamin A is involved in determining stemness in seminomas." (PMID 34771736, 2021). "NANOG immunostaining is usually detected in the nuclei of pluripotent cells, as shown in our seminoma control." (PMID 28894270, 2017). "ECs and seminomas express the pluripotency markers NANOG and OCT3/4, but SOX2 is detected in ECs only and is thought to be compensated by SOX17 in seminomas." (PMID 27283990, 2016). "Pluripotency and seminoma markers like NANOG, OCT3/4, LIN28, TFAP2C, cKIT, D2-40 and PRDM1 were downregulated." (PMID 27283990, 2016). "The core stemness transcription factors POU5F1 and NANOG which are expressed in both, seminoma and non-seminoma tumor cells are thought to be pivotal for the identification of TGCT." (PMID 23969837, 2013). "Current models of GCT differentiation suggest that embryonal carcinoma and seminoma are the undifferentiated types of tumors and that they share many features with normal embryonic stem cells including expression of pluripotency factors such as NANOG, POU5F1, and SOX-2 among others." (PMID 24475288, 2014). "Overall, seminomas more strongly resemble PGCs and express pluripotency genes, particularly OCT3/4, SOX2, and NANOG." (PMID 38791003, 2024). "We found that seminoma and PGCs display strong similarities in their transcriptomes, especially by sharing the expression of key TFs such as TFAP2C, POU5F1, NANOG and SOX17." (PMID 38123589, 2023). "As expected, seminoma and PGCs shared specific expression of genes (C2) such as TFAP2C, POU5F1, NANOG and SOX17." (PMID 38123589, 2023). "qPCR measurements revealed that FLNA-deficient cells show enhanced transcript levels of the stem cell markers OCT3/4, NANOG and FGFR3 in comparison to TCam-2 WT seminoma cells." (PMID 33266100, 2020). "Both, seminomas and EC express the pluripotency markers OCT3/4 and NANOG, but expression of the pluripotency factor SOX2 is restricted to ECs, while seminomas express SOX17 instead." (PMID 26226633, 2015). "In contrast, non-seminomas are transformed germ cells that have reactivated pluripotency, as evidenced by the expression of SOX2, OCT3/4 and NANOG, three main regulators of pluripotency." (PMID 23068969, 2012). "NANOG is another marker that can be used to detect GCNIS, seminoma and embryonal carcinoma." (PMID 41384700, 2026). "Additionally, strong and comparable expression of the seminoma and pluripotency markers OCT3/4, NANOG, LIN28, SOX17, PRAME, PRDM1/BLIMP1 and TFAP2C was found in TCam-2, TCam-2-ΔSOX2 and TCam-2-ΔSOX2/FOXA2 cells." (PMID 31130628, 2019). "However, with downregulation of PGC- (PRDM1, TFAP2C, cKIT) and pluripotency (NANOG, OCT3/4, LIN28) marker genes, persisting SOX17 expression together with activation of the Hippo pathway resulted in differentiation into a mixed non-seminoma with predominant choriocarcinoma-like components." (PMID 26226633, 2015). "Although Tcam-2 cells are not identical to seminomas in vivo, solid analogies exist regarding the expression of stem cells markers such as OCT4, NANOG, PLAP, KIT, and D2-40." (PMID 35269507, 2022). "Similar to seminomas, non-seminomas express OCT3/4 and NANOG, with the addition of SOX17." (PMID 38791003, 2024).
seminoma (continued). "Furthermore, seminomas have elevated levels of GDF3 expression compared to the normal testis, as well as other stem cell markers such as Nanog homeobox (NANOG) and octamer-binding transcription factor 4 (OCT4), and in particular DAZL (a germ cell-specific marker)." (PMID 37205315, 2023).
lung carcinoma (33 papers, 2011 to 2025). "The expression of OCT4 on CD133+ cells in the lung cancer is associated with tumorigenesis and metastasis, and overexpression of NANOG is associated with a worse prognosis." (PMID 34685477, 2021). "Similar to our observations, coexpression of OCT4 and NANOG was found to be significantly associated with tumor aggressiveness and poor prognosis of several malignances including breast and lung cancers and glioma." (PMID 30082842, 2018). "Overexpression of NANOG has been seen in several solid human cancers, such as breast, brain, colon, and lung cancer." (PMID 39547513, 2024). "Lung cancer stem cells (derived from the H460 cell line) downregulate their expression of stemness genes NANOG and OCT-4 after 6 h of RPM exposure." (PMID 37048115, 2023). "It is worth noting that the expression patterns of NANOG seem different between human and murine lung cancers, e.g., nuclear NANOG expression is observed in mouse model but rarely detectable in human lung cancer specimens." (PMID 33439550, 2021). "In contrast to the nuclear location detected in the mouse model, NANOG was mainly expressed in the cytoplasm of human lung cancer cells, indicative of different expression patterns in different species." (PMID 33439550, 2021). "When we overexpressed full‐length human NANOG cDNA in human lung cancer cell lines, we found that the exogenous NANOG expression produced 3 different bands, two around 40 kDa and another one around 25 kDa." (PMID 33439550, 2021). "1,2,3-Triazole–containing agent CAI synergizes with sorafenib to combat NSCLC through the inhibition of NANOG and aggravation of apoptosis, indicating that 1,2,3-triazole–containing derivatives are useful scaffolds to develop novel anti–lung cancer agents." (PMID 34177578, 2021). "Despite the importance of NANOG in lung cancer progression and in regulating CSC properties, the relevance between NANOG with EGFR-TKI resistance is yet unclear." (PMID 32820157, 2020). "Of note, the protein level of NANOG in lung cancer tissues was upregulated compared to the normal lung tissues and NANOG overexpression predicted a worse prognosis for lung cancer patients." (PMID 32820157, 2020). "We determined mRNA expression levels of the stemness genes NANOG and Oct4B, and also of the putative lung cancer stem cell markers CD44 and CD133." (PMID 26895954, 2016). "Moreover, lung cancer cells treated with SM-3 exhibited decreased mRNA expression levels of the transcription factors NANOG, OCT4, and SOX2." (PMID 40287470, 2025). "OCT-4 and NANOG regulate the stemness properties of tumour and promote metastasis in lung cancer." (PMID 41376750, 2025). "The TF-protein NANOG is reported as a prognostic biomarker for lung cancer." (PMID 39024368, 2024). "In lung cancer, NANOG expression correlates with TNM stage, tumor differentiation, and survival." (PMID 35719973, 2022). "Similarly here, it will be important to further understand the differences of NANOG expression and function between mouse and human lung cancer pathogenesis for future preclinical studies." (PMID 33439550, 2021). "Furthermore, various studies have also reported increased expression levels of NANOG in cancer stem cells in other types of cancers, such as breast and lung cancers, supporting that NANOG and NANOGP8 are established cancer markers." (PMID 29787607, 2018). "Moreover, coexpression of OCT4 and NANOG is a strong independent predictor of unfavorable outcome and tumor recurrence in HCC patients and is associated with enhanced lung cancer malignancy and pancreatic carcinogenesis." (PMID 30082842, 2018). "According to western blot and immunofluorescence analyses, SM-3-treated human lung cancer cells (A549, H292, and H460) showed decreased levels of stem cell markers (CD44, CD133, ALDH1 A1) and stem cell transcription factors (NANOG, OCT4, SOX2)." (PMID 40287470, 2025).
lung carcinoma (continued). "In our research, lung cancer cells treated with DH_32 exhibited a reduction in the mRNA expression levels of the OCT4, NANOG, and SOX2 transcription factors." (PMID 38132948, 2023). "In the study of lung cancer, it was found that when ENPP1 gene was knocked out in lung cancer cell lines, the expression of a large number of stem cell markers decreased, including ABCG2, SOX2, NANOG, and CD44." (PMID 33635867, 2021). "Immunohistochemically assessed cell positivity for ALDH1A1, SOX2, NANOG, OCT-4, and c-MYC, which are considered as lung cancer stem-like cells markers." (PMID 32500024, 2020). "Corresponding to previous studies, we isolated SP cells with high mRNA expression of ABCG2, OCT4, and NANOG genes and high proliferative potential from gefitinib-resistant NCI-H460 lung cancer cells." (PMID 28219421, 2017). "Likewise, the mRNA results showed that SM-3 substantially reduced the levels of the transcription factors OCT4, NANOG, and SOX2 compared to Res-treated lung cancer cells, including H292 and H460 cells." (PMID 40287470, 2025). "Additionally, SM-3 treatment resulted in decreased expression of stem cell markers (CD133, CD44, and ALDH1A1) and transcription factors (OCT4, NANOG, and SOX2) in spheroids and organoids from human lung cancer cells by inhibiting the mTOR/pAkt pathway." (PMID 40287470, 2025). "Similarly, coculturing lung cancer cells with THP1-derived macrophages resulted in significant increases in SOX2, OCT4, and NANOG expression in cancer cells and M2-like polarization of TAMs." (PMID 39287565, 2024). "In lung cancer, many studies have shown that intracellular transcription factors, such as SOX2, OCT4, and NANOG, are maladjusted and may therefore activate stemness genes and suppress differentiation genes." (PMID 35719973, 2022). "Our data show that NANOG is expressed in KL mouse model and functionally important in maintaining lung cancer stemness; however, it is not significantly expressed in human lung ADC." (PMID 33439550, 2021). "In lung cancer cell lines, down-regulation of NEAT1 could decrease the expression of stemness-related factors, including CD133, CD44, SOX2, OCT4 and NANOG." (PMID 33614649, 2021). "Targeted overexpression or knockdown of miR-221/222 in NSCLC cells revealed the essential roles of miR-221/222 in regulation of lung cancer cell proliferation, mammosphere formation, subpopulation of CD133+ CSCs and the expression of stemness genes including OCT4, NANOG and h-TERT." (PMID 33959615, 2021). "Notably, the mRNA expression levels of both NANOG and SOX2 were found to be downregulated in subpopulations of cancer stem cells isolated from lung cancer tissue specimens." (PMID 32635524, 2020). "The activities (ssGSEA scores) of both pluripotency factors (NANOG, MYC) and mitochondrial biogenesis are higher in CSCs compared with non-CSCs in skin squamous cell carcinoma (SCC) and lung cancer (GSE108679 and GSE136580, respectively)." (PMID 37463926, 2023).
embryonal carcinoma (32 papers, 2011 to 2026). A non-seminomatous malignant germ cell tumor characterized by the presence of large germ cells with abundant cytoplasm resembling epithelial cells, geographic necrosis, high mitotic activity, and pseudoglandular and pseudopapillary structures formation. "Similarly, it was shown recently that there is loss of H3K4me3 on NANOG gene upon human embryonal carcinoma NT2/D1 cell differentiation towards neural progenitors." (PMID 31765427, 2019). "NTERA-2 cells, a pluripotent human embryonic carcinoma cell line, were NANOG-, OCT4A- and SOX2-positive." (PMID 36900355, 2023). "Activation of NANOG by its small activating RNAs has also been shown to maintain embryonic carcinoma cells in an undifferentiated state in the presence of retinoic acid." (PMID 35246011, 2022). "NANOG is highly expressed in pluripotent cells, such as ESCs and embryonal carcinoma cells, and its expression is downregulated upon differentiation." (PMID 32168958, 2020). "For example, SP1, previously implicated in tumorigenesis and cell cycle regulation, and as a regulator of NANOG expression in murine embryonic carcinoma cells." (PMID 33256189, 2020). "Previous studies on HDACi-treated stem cells and embryonal carcinoma cells showed a connection between downregulation of NANOG and inhibition of proliferation, however, the exact relation between cell cycle arrest and NANOG suppression is not yet known." (PMID 23969837, 2013). "Another study detailed the transcriptional properties of NANOG in a human embryonal carcinoma cell line, revealing additional exons at the 5’ end beyond the known gene structure." (PMID 25077040, 2012). "The transfection of MIR630 into embryonic carcinomas suppressed NANOG." (PMID 36497144, 2022). "NANOG was shown to promote tumorigenesis in embryonic carcinomas." (PMID 36497144, 2022). "Moreover, in constitutively NANOG-overexpressing human embryonal carcinoma cells (NT2/D1 and NCCIT), NANOG expression was repressed by PKC activation." (PMID 35008480, 2021). "Since high NANOG expression is associated with poor differentiation of solid tumors, it was interesting to know whether MIR630 promotes the differentiation of embryonal carcinoma cells." (PMID 35008480, 2021). "However, LEFTY2 is a key factor in various developmental processes and a previous knockdown study from our group reported an up-regulated expression of LEFTY2 after siRNA mediated knockdown of OCT4 or NANOG in the embryonal carcinoma cell line NCCIT." (PMID 25369332, 2014). "Human embryonic stem cells and human embryonal carcinoma cells have been studied extensively with respect to the transcription factors (OCT4, SOX2 and NANOG), epigenetic modulators and associated signalling pathways that either promote self-renewal or induce differentiation in these cells." (PMID 25369332, 2014). "Another recent study has also reported a similar AS event in the human NANOG gene in embryonal carcinoma cells from an upstream region at the 5’ region, resulting in additional transcripts and a protein variant that initiates from a downstream methionine and is the human ortholog of mouse Nanog c." (PMID 25077040, 2012). "Additionally, GDF3 is a direct transcriptional target of NANOG in embryonic carcinoma cells." (PMID 37205315, 2023). "In addition to rhabdomyosarcoma cell lines, we also examined established and patient-derived tumor cell lines of neurogenic origin, as well as the NTERA-2 human pluripotent embryonal carcinoma cell line, which served as a positive control of nuclear NANOG expression." (PMID 32168958, 2020). "NANOG is specifically expressed in the human embryonic pluripotent stem cells of embryos prior to or following implantation, primordial germ cells, ES cells cultured in vitro, embryonic germ cells and embryonic carcinoma cells, and functions in the promotion of cell proliferation." (PMID 25120646, 2014).
embryonal carcinoma (continued). "OCT3/4, NANOG, SOX2, GP-3, and CD30 markers can help reliably differentiate yolk sac tumors and embryonal carcinomas." (PMID 37443818, 2023). "Experimentally, we showed that transfection of MIR630 mimic into embryonal carcinoma cell lines directly targeted the 3′UTR of OCT4, SOX2, and NANOG and markedly suppressed their expression." (PMID 35008480, 2021). "Human embryonal carcinoma cells (hEC), have substantial similarities with hESC with respect to self-renewal, gene expression signature (e.g. OCT4, LIN28 and NANOG), surface antigens as well as alkaline phosphatase activity." (PMID 25369332, 2014). "In contrast, when human embryonal carcinoma-derived (hEC) 2102Ep cells were treated with sodium butyrate, they continued to express high levels of SSEA-3, SSEA-4, NANOG, OCT4, and SOX2." (PMID 24707296, 2014). "After treatment with ATRA, known to induce differentiation of embryonal carcinoma NT2 cells, LIN28 expression was significantly downregulated, as it happened with pluripotency factors NANOG and POU5F1, with the opposite occurring for PAX6, a marker of differentiation." (PMID 40448114, 2025). "In keeping with a restricted expression of RARγ within primitive cells, the binding sites for RAR/RXR dimers within undifferentiated F9 embryonal carcinoma cells coincided with loci that are targeted by transcription factors that are important to pluripotency (SOX2, NANOG, and POU5f1)." (PMID 37082619, 2023). "In the current study, the epigenetic role of nuclear actin ontranscription regulation of two stemness (OCT4 and NANOG)and two differentiation) NESTIN and PAX6) marker genes was evaluated in a human embryonal carcinoma cell line (NT2)before and after differentiation induction." (PMID 27540526, 2016). "NANOG is expressed in dysgerminoma and embryonic carcinoma, but not in immature teratoma, endodermal sinus tumors or choriocarcinoma." (PMID 25120646, 2014). "That NT2-D1 cells also express NANOG and POU5F1, and can also be induced to differentiate with a subsequent decrease in expression of these factors, supports the hypothesis that these cells represent a true embryonal carcinoma cell line." (PMID 24475288, 2014). "Positive staining for CD30, OCT3/4, NANOG, SOX2 GP-3, or CD30 tends to occur more commonly among embryonal carcinomas while negative staining occurs more commonly among yolk sac tumors, serving as reliable indicators between them both neoplasms." (PMID 37443818, 2023). "Western blot analysis verified the presence of OCT4, SOX2 and NANOG in hiPSCs and NT2 cells (pluripotent embryonal carcinoma cells, as a positive control), as well as the absence of α-SMA and GFAP." (PMID 30518391, 2018).